PDK1 (pyruvate dehydrogenase kinase 1)
Diseases named in the same sentence as PDK1 in open-access papers (continued):
Sharing a sentence is not in itself a finding about the gene and the disease.
cancer (continued). "Similarly, the PI3K pathway independent of AKT has also been demonstrated to promote different cancers via mTOR, PDK1 and cMyc." (PMID 29401696, 2018). "Hence, we demonstrate here that Akt-independent PDK1 signaling pathways regulate the subcellular localizations of de novo purine biosynthetic enzymes in cancer cells." (PMID 29668719, 2018). "Since PDK1 is a critical enzyme regulating glycolytic metabolism in cancer cells, we next sought to determine whether PDK1 is involved in Chibby-mediated changes in glycolysis." (PMID 29764469, 2018). "Finally, several metabolic enzymes that regulate glycolysis are highly expressed in cancer, including pyruvate dehydrogenase kinase 1 (PDK1) and phosphofructokinase 2 (PFK2), allowing cancer cells to easily adapt glycolytic flux to meet their needs." (PMID 30456204, 2018). "In addition, the PDK1–Akt axis regulates chemotaxis of MDA-MB-231 cancer cells toward epidermal growth factor (EGF) and of T-cells; the same axis regulates neocortical neurons locomotion in developing mammalian neocortex." (PMID 28287465, 2017). "Indeed, it has been recently shown that GSK2334470 (GSK-470), a novel and highly specific inhibitor of PDK1, inhibits growth, induces cell cycle arrest and overcomes drug resistance in human cancer cells." (PMID 28402933, 2017). "Recent studies also suggest that PDK1 inhibitors may have other benefits, including reduction of cancer cell resistance to chemotherapeutic drugs, such as Tamoxifen." (PMID 28430130, 2017). "In addition, inhibition of PDK1 with either siRNAs or inhibitor shifts the metabolism of cancer cells from glycolysis to mitochondrial respiration." (PMID 28899927, 2017). "In this study, we suggested that AAE may exert cancer cell apoptosis through PTEN/PDK1/Akt/p53signal pathway and mitochondria-mediated apoptotic proteins." (PMID 28454566, 2017). "This speculation is based partially on the findings that cancer cells pre-exposed to IH showed up-regulated expression of PDK1, revealing that those pre-trained cells were relatively prepared to adapt to IH conditions." (PMID 28977888, 2017). "The aim of this review is to summarize the various mechanisms by which PDK1 controls the cell migration process, from cell polarization to actin cytoskeleton and focal adhesion regulation, and finally, to discuss the evidence supporting a role for PDK1 in cancer cell invasion and dissemination." (PMID 28287465, 2017). "In PIK3CA mutant cancer cell lines and in human breast tumors, PDK1 may activate an alternative signal that engages downstream substrates such as SGK3." (PMID 28287465, 2017). "Moreover, PDK1 regulates cancer cell invasion as well, thus representing a possible target to prevent cancer metastasis in human patients." (PMID 28287465, 2017). "Currently, AKT is considered to be the main effector of PDK1 in cancer, thereby targeting PDK1 may provide an opportunity for developing novel therapeutics for cancer." (PMID 28402933, 2017). "PDK1 can be also implicated in chemoresistance through another PDK1-binding protein, the tongue cancer resistance-related protein-1 (TCRP1), the levels of which are found to be increased in a number of cancers including pancreatic and ovarian ones." (PMID 29064423, 2017). "ROCK1 activated by PDK1 regulates amoeboid-type cancer cell invasion." (PMID 28287465, 2017). "According to the experimental evidence accumulated so far, and reviewed here, PDK1 targeting could be effective to block cancer progression towards a more invasive and metastatic phenotype." (PMID 28287465, 2017). "Indeed, the regulation of PDK1 activity is well-orchestrated in cancer cells: mRNA levels of PDK1 are regulated by hypoxia-inducible factor-1 and Myc, whereas the phosphorylation of PDK1 by oncogenic tyrosine kinases promotes PDK1 activity." (PMID 27462466, 2016). "An increasing number of studies suggest that PDK1 inhibitors may be useful to prevent cancer progression and abnormal tissue dissemination." (PMID 27551332, 2016).
cancer (continued). "Moreover, depletion of RNF126 or increased expression of PDK1 in cancer cells suppressed colony formation in soft agar as well as tumorigenicity in mice." (PMID 27462466, 2016). "Moreover, PDK1 depletion is effective in eradicating cancer by activation of oncogene-induced senescence." (PMID 25601413, 2015). "The PDK1 substrates Akt1, Akt2, and Akt3 are highly expressed in several types of human cancers." (PMID 26318166, 2015). "This led us to investigate whether the PV-inducible PKCη/Rdx-mediated phosphorylation of PDK1 at S138 (in mouse) or S135 (in human) might be a cancer pathway leading to constitutive PDK1 activation." (PMID 25742010, 2015). "There is increasing evidence that PDK1 is involved in cancer progression and invasion." (PMID 26684827, 2015). "The protein 3-phosphoinositide-dependent protein kinase 1 (PDK1) is upregulated in cancer." (PMID 26318166, 2015). "Thus, despite its universal role in cell homeostasis, accumulating evidence points to PDK1 as a valid target for cancer therapy." (PMID 25742010, 2015). "Inhibition of PDK1 in several cancer cells results in significant cell growth inhibition." (PMID 24925061, 2014). "In our in vivo study, PDK-1 expression correlated with cancer progression and patient prognosis." (PMID 23135628, 2013). "However, this treatment led to significant metabolic changes in only the MKN45 cancer cell line, where it resulted in increased lactate production and greater PDK-1 expression." (PMID 23135628, 2013). "Previous reports show that HIF-1α activates pyruvate dehydrogenase kinase (PDK)-1 under hypoxic conditions that regulates mitochondrial oxygen consumption in cancer cells by inhibiting pyruvate dehydrogenase, the enzyme responsible for converting pyruvate into acetyl CoA." (PMID 23840849, 2013). "Compared to AKT, there are few studies of PDK1 in human cancers." (PMID 22666248, 2012). "Furthermore, inhibition of PDK1 in cancer cells in vitro and in vivo results in a reduction of phosphorylated PDH and HIF-1α levels." (PMID 21541279, 2011). "InsP5 and 2-O-Bn-InsP5 may represent lead compounds to develop novel inhibitors of the PI3K/Akt pathway (including potential dual PDK1/mTOR inhibitors) and novel potential anti-cancer drugs." (PMID 20051961, 2010). "PDK-1/AKT pathway may be an attractive therapeutic target for cancer intervention in RMS using OSU-03012." (PMID 17848913, 2007). "Notably, PDK1 is known to influence immune cell function in some cancers." (PMID 40971960, 2025). "In this context, targeting PDK1 may sensitize cancer cells to therapy." (PMID 40649898, 2025). "Thus, ABCG1 may confer cell stemness and maintain stem‐like properties by enhancing aerobic glycolysis of malignant tumors through the HIF‐1a/PDK1 signaling axis." (PMID 38896016, 2024). "Therefore, a co-blockade of PI3K and PDK1 may provide a more effective therapeutic approach to treat cancers." (PMID 37531320, 2023). "Besides, by enhancing PDK1 protein expression, MAPK4 may further enhance the canonical PI3K-PDK1-AKT pathway to promote cancer growth." (PMID 37531320, 2023). "To examine whether MAPK4 plays a major role in regulating PDK1 protein stability, we first examined PDK1 protein stability in 7 TNBC cancer cell lines, including the MAPK4-low HCC1806, MDA-MB-468, HCC1395 cells, and the MAPK4-medium/high SUM159, MDA-MB-231, HCC1937, and HS578T cell lines." (PMID 37531320, 2023). "Therefore, TMEM116 promotes cancer development via the PDK1/AKT/FOXO3A signaling pathway." (PMID 37367036, 2023). "Thus, the inhibition of PDK1 is more promising than AKT as a new target for cancer therapy." (PMID 37107587, 2023). "Therefore, it is crucial to understand how PDK1 protein expression is regulated in human cancers." (PMID 37531320, 2023). "Given the essential role of PDK1 in signal transduction downstream of growth factors and upstream of Akt, the development of allosteric inhibitors that target PDK1 may have enormous implications in the treatment of cancer." (PMID 35387990, 2022).
cancer (continued). "In addition, genetically depleting or pharmacologically inhibiting AKT1 could robustly attenuate PDK1-S549A-induced cancer cell colony formation." (PMID 35318320, 2022). "Furthermore, PDK1 mediates chemoresistance in different cancer cell types by the activation of several oncogenic pathways, namely Polo-like kinase-1 (PLK1)- myelocytomatosis (MYC) Axis, Yes-associated Protein (YAP)/Hippo Pathway, and the serum and glucocorticoid inducible protein kinase (SGK) Axis." (PMID 36076967, 2022). "Overexpression of PDK1 in cancer cells inhibits PDC-catalyzed tricarboxylic acid cycle, resulting in the inability of aerobic oxidation, may cause cancer cells prefer other material as their new energy source or other metabolic pathway to obtain large amounts of energy substances." (PMID 33403023, 2021). "In addition, TMEM116 deficiency inhibited PDK1-AKT-FOXO3A signaling pathway, resulting in accumulation of TAp63, while activation of PDK1 largely reversed the TMEM116 deficiency induced defects in cancer cell motility, migration and invasive." (PMID 34789718, 2021). "PDK1 is involved in the physiological regulation of transcription regulation, protein synthesis, cell migration, cell growth, differentiation, proliferation and apoptosis, and may be a viable cancer biomarker." (PMID 33739396, 2021). "Consistent with these, PDK1 has been shown to be dysregulated in some malignancies, and accruing evidence suggesting that the underexplored PDK1 may serve as a therapeutic target and is a probable modulator of sensitivity to cancer therapy." (PMID 32197467, 2020). "In addition to inducing apoptosis and inhibiting cell division and proliferation by blocking several proliferation-stimulating signaling pathways, it also activates the PDK1/Akt/mTOR survival pathway, which severely compromises ponatinib as an anti-cancer drug." (PMID 30959969, 2019). "HIF1 can also allow cancer cells to rely on oxygen consumption by activating glycolytic metabolism, and inhibiting mitochondrial oxidative phosphorylation against low oxygen availability, by upregulating pyruvate dehydrogenase kinase 1 (PDK1), which suppresses respiratory ROS generation." (PMID 31540530, 2019). "However, the link between Wnt/β-catenin and PDK1 in these cancer cells, as well as NPC cells is still unknown." (PMID 29764469, 2018). "Therefore, the present study may suggest that the metabolic function of the 3-enzyme core assembly is controlled by the spatially resolved activity of PDK1 for cancer cell survival, migration and invasion." (PMID 29668719, 2018). "PDK1 independent of PI3K can also cause cMyc phosphorylation in cancer cells." (PMID 29401696, 2018). "Therefore, it is imperative to develop potent PDK1 inhibitors with a high safety profile and minimal side effects as well as to examine their antitumor activities to assess their therapeutic potential in cancer treatment." (PMID 28617852, 2017). "Thus, TCRP1 may be a candidate as human oncoprotein that promotes cancer development by activation of PDK1/AKT1 signaling." (PMID 28436990, 2017). "Moreover, a pivotal role for PDK1 in cancer progression has emerged in recent years." (PMID 28287465, 2017). "Nevertheless, it was found that the responsiveness of the cells to this inhibitor was proportionally correlated to the expression status of PTEN, supporting the idea that following loss of PTEN, sole PDK1 inhibition does not suffice to hamper cancer progression." (PMID 29064423, 2017). "PDK1 inhibitors may be useful to prevent cancer progression and abnormal tissue dissemination." (PMID 28210221, 2017). "In parallel with this, PDK1 could serve well in the field of cancer biomarker discovery, and more specifically act as a pharmacodynamic (PD) biomarker, in order to measure the biological activity of a protein-target, following treatment with an inhibitor- candidate." (PMID 29064423, 2017).
cancer (continued). "Previously, the phenethyl ester of caffeic acid (CAPE) was reported to modulate PDK1 at the level of its gene expression in a context of induction of hypoxia via hypoxia-inducible factor 1α (HIF1α), which might have influenced cancer cell adaptation to metabolic demands." (PMID 28230778, 2017). "Thus, RNF126 depletion may diminish tumorigenicity of cells mainly by affecting the fine-tuning of PDK1 activity in cancer cells." (PMID 27462466, 2016). "Previous studies have shown that PDK1 may be a viable cancer biomarker." (PMID 26318166, 2015). "Thus, the PDK1/Akt signaling pathway represents an attractive target for the development of small molecule inhibitors that may be useful in the treatment of cancer." (PMID 26684827, 2015). "The upregulation of glycolysis through HIF1α target genes (such as HK2, GLUT1, PDK1, and LDHA) provides cancer cells with rapid ATP production and biosynthetic intermediates." (PMID 39807625, 2025). "In PTEN-intact cancer cells with low AKT activity, PI3K mainly utilizes AKT-independent signals via PDK1 and serum/glucocorticoid-regulated kinase-3 (SGK3)." (PMID 40427140, 2025). "The regulation of HIF1α, LDHA, and PDK1 by the ZFAS1-STAT3 axis is a novel insight that can have significant implications for understanding and targeting cancer metabolism." (PMID 40697388, 2025). "CDK1 has been shown to phosphorylate and regulate distinct functions of several substrates, including disruptor of telomeric silencing 1-like (DOT1L), SRY-box transcription factor 2 (SOX2), and pyruvate dehydrogenase kinase 1 (PDK1), in various cancers." (PMID 40695806, 2025). "OSU-03012, also known as AR-12, is an orally active pyruvate dehydrogenase kinase isoenzyme 1 (PDK-1) and protein kinase B (AKT) signaling pathway inhibitor that reached Phase 1 clinical trials as a potential cancer therapeutic." (PMID 41278872, 2025). "In radioresistant Huh7-R cells, PDK1 upregulation correlates with 24.16-fold increased ALDH1 activity and 7.03-fold higher side population cell proportions, indicating its role in cancer stemness." (PMID 40725100, 2025). "By targeting PDK1 with agents such as LY294002, YC-1, leelamine, and DCA in combination with osimertinib, we demonstrated a synergistic approach for sensitizing cancer cells to osimertinib." (PMID 38689087, 2024). "The targets for HIF-1α include LDH-A, PFKFB3, PDK-1, and PDK-3; therefore, the expression and activities of these proteins are increased in cancer cells." (PMID 38339256, 2024). "Expression of the PDK1 gene is upregulated by hypoxia-inducible factor-1α (HIF-1α), an important mechanism by which cancer cells switch from oxidative to anaerobic glucose metabolism." (PMID 39080182, 2024). "Co-inhibition of PDK1 and PI3K remained the most synergistic combination, indicating the essential role of full PI3K pathway inhibition for cancer suppression." (PMID 38273040, 2024). "This study is the first to provide a theoretical framework and guidance for the possible use of a novel PH domain inhibitor of PDK1, CU05-1189, as a treatment for angiogenesis-related diseases such as cancer." (PMID 38035024, 2023). "Henceforth, HIF-1α, through direct regulation of PDK1, LDHA, and MCT-4, effectively saves cancer cells from acidosis and harmful reactive oxygen species." (PMID 36891273, 2023). "By enhancing PDK1 protein expression, MAPK4 both activates PDK1 substrates beyond AKT and supports the PI3K-PDK1-AKT signaling cascade to regulate cancer cell biology." (PMID 37531320, 2023). "Co-targeting AKT and PDK1 can therefore repress MAPK4-induced cancer cell growth, suggesting a potential therapeutic strategy to treat MAPK4-high cancers, including a large subset of "triple negative" breast cancer." (PMID 37531320, 2023). "Phosphoinositide-dependent kinase-1 (PDK1) is a master kinase of the protein A, G, and C (AGC) family kinases that play important roles in regulating cancer cell proliferation, survival, and metabolism." (PMID 37531320, 2023).
cancer (continued). "This included ERα, the transcriptional repressor protein E2F-4, the microtubule protein αTubulin and proteins involved in cancer cell metabolism (GLUT1, LDHA and PDK1-pSer241) and stress responses (eIF2A-pSer51)." (PMID 37596623, 2023). "Using pyruvate dehydrogenase kinase-1 (PDHK1), a well-defined HIF-1 target gene that is frequently involved in cancer metabolism reprogramming, we found that Control Clone A PDHK1 is upregulated after 8 h of hypoxic exposure." (PMID 36935009, 2023). "NDDs and cancer signal through common cellular pathways, including MAPK and PI3K/ PDK1/AKT/mTOR with phosphatase and tensin homolog (PTEN), critical in cell division and growth, thus proliferation and cell differentiation." (PMID 37124926, 2023). "A recent study demonstrated that AKT activates PDK1 in hypoxic tumors and promotes tumorigenesis, providing a rationale for the combined targeting of AKT and PDK1 in cancer." (PMID 37458534, 2023). "Since MAPK4 can PI3K/PDK1-independently activate AKT, we predicted and experimentally validated that MAPK4 renders cancer cell resistance to PI3K blockade." (PMID 37531320, 2023). "To test the direct regulatory link, we knocked down HDAC2 and EZH2 expression using siRNAs in the cancer cell lines, and found that EZH2 and HDAC2 silencing in the cells significantly decreased PDK1 expression." (PMID 35892859, 2022). "They found that LIN28AB enhances, while let-7 suppresses, aerobic glycolysis by targeting pyruvate dehydrogenase kinase 1 (PDK1), demonstrating a novel pathway to mediate aerobic glycolysis of cancer cells." (PMID 35806250, 2022). "In a study of cancer, it was demonstrated that the overexpression of PDK1 results in a decrease in the activity of PDH, affects the metabolic state of cancer cells, and promotes the growth, survival, and invasion of cancer cells." (PMID 35887737, 2022). "HNK reduced the expression of HIF-1α, GLUT1, HK2 and PDK1, decreased ECAR, increased OCR, and decreased glucose uptake, lactate production and ATP production in cancer cells." (PMID 35350760, 2022). "In summary, our findings not only reveal an important feedback regulation of S6K on PDK1/AKT signaling pathway by directly phosphorylating PDK1, but also provide a potential strategy to combat gain-of-function mutant PDK1-driven cancers." (PMID 35318320, 2022). "Several PDK1 substrates belong to the PI3K (Akt, Sgk) or MAPK pathways (RSK), both of which are frequently dysregulated in human cancers." (PMID 35387990, 2022). "Recent research showed that miR-375 is strongly downregulated in a wide range of cancers and that it suppresses carcinogenesis by targeting various critical oncogenes including AEG-1, YAP1, IGF1R, and PDK1." (PMID 36157234, 2022). "PDK1 is an important regulator for the Warburg effect, primarily regulating pyruvate dehydrogenase (PDH) activity which is induced in human cancers and represents a plausible anticancer therapeutic strategy." (PMID 35892859, 2022). "Studies have reported that PDK1 and PDK2 inhibition suppresses the growth, motility, and drug resistance of cancer cells." (PMID 36474273, 2022). "The Cancer Proteome Atlas (TCPA) created a Kaplan Meier (KM) plot for miR-520c-3p targets AKT1, AKT2, AKT3, MTOR, NF-κB (RelA), PDK1, PI3K, and PTEN." (PMID 35634241, 2022). "Regarding binding affinity, PDK4 has the lowest affinity, PDK3 has the highest affinity, PDK1 and PDK2 have medium affinity, and PDK1-3 can interact with various signal transduction factors, which is helpful in cancer progression." (PMID 35957825, 2022). "It targets certain oncogenes, such as AEG-1/MTDH, PDK1, YWHAZ/14-3-3ζ, YAP and JAK2, in multiple types of carcinomas." (PMID 35205648, 2022). "Similar to PDK1, PDK3 also participate in the metabolic switch of cancer cells, and has recently been considered as a potential pharmacological target for varying types of cancers." (PMID 33739396, 2021).